IL6 (interleukin 6)
Diseases named in the same sentence as IL6 in open-access papers (continued):
Sharing a sentence is not in itself a finding about the gene and the disease.
rheumatoid arthritis (continued). "For example, serum IL-6 levels are increased in patients with cardiovascular problems and in Alzheimer’s disease, rheumatoid arthritis, and chronic kidney disease (CKD), thereby suggesting that elevated levels of IL-6 contribute to chronic inflammation." (PMID 23922826, 2013). "It is known that IL-6 plays a critical role in the pathogenesis of autoimmune diseases, and overproduction of IL-6 has previously been described in rheumatoid arthritis in humans." (PMID 23667522, 2013). "The relevance of IL-6 in contributing to the pathogenesis of inflammatory disease is further supported by the therapeutic effect of tocilizumab on patients with rheumatoid arthritis." (PMID 23956869, 2013). "Most importantly, the expressions of key proinflammatory genes such as Il6, Vcam1, Ccl7, Mmp3, Mmp13, enhanced in rheumatoid arthritis and osteoarthritis, were reduced." (PMID 24199619, 2013). "Elevated levels of IL-6 have been documented in a variety of autoimmune diseases, such as rheumatoid arthritis, inflammatory bowel disease, glomerular nephritis, and so forth." (PMID 24082909, 2013). "Overproduction of IL-6 plays a role in rheumatoid arthritis, juvenile idiopathic arthritis, inflammatory bowel disease, and SLE." (PMID 24453431, 2013). "Blockade of IL-6 in rheumatoid arthritis patients led to reduced disease activity and substantial improvement in clinical signs further strengthening the therapeutic potential of IL-6 modulation." (PMID 24155968, 2013). "This assumption is based on the observation of a correlation of IL-6 serum levels with disease activity in rheumatoid arthritis, Crohn's disease, asthma, and psoriasis." (PMID 23956869, 2013). "Recombinant IL6 blockers have been successfully applied to treat rheumatoid arthritis, and this study indicates the need for further investigation into IL6, as a potential target for therapeutic intervention in tendinopathy." (PMID 22092479, 2013). "Rheumatoid arthritis (RA) is a chronic autoimmune disease associated with production of elevated levels of pro-inflammatory cytokines, including IL-12, IL-6, IL-1, IL-23, and TNFα, that are involved in activation of naïve T cells and directing their polarization into TH1 and TH17 cells." (PMID 22969767, 2012). "Higher levels of IL-6 have also been shown to correlate with osteoporosis and other bone deficits in patients with chronic inflammatory diseases such as rheumatoid arthritis and inflammatory bowel disease, as well as patients who underwent HCT." (PMID 22455440, 2012). "The inhibitory effect on TNF-α and IL-6 production by magnolol may contribute to the bone antiresorbing effect of magnolol and possibly also play a role in the reduction of bone loss seen in the vicinity of inflammatory processes such as rheumatoid arthritis and periodontal disease." (PMID 22474400, 2012). "IL-6 is involved in joint pain and rheumatoid arthritis, and it increases the production of cartilage-destroying enzymes." (PMID 22479654, 2012). "MR16-1 is a rat anti-mouse IL-6R antibody that competitively inhibits the binding of IL-6 to IL-6R dose-dependently, has a half-life of about 3 days in mice, and exhibits anti-inflammatory properties in rheumatoid arthritis and SCI." (PMID 22369693, 2012). "Glucose-6-phosphate isomerase (GPI)-induced arthritis is a closer model of human rheumatoid arthritis based on its association with CD4+ T cells and cytokines such as TNF-α and IL-6 than CIA." (PMID 23251456, 2012). "Increased levels of IL-6 and sIL-6R have been found in synovial fluids and sera from osteoarthritis and rheumatoid arthritis patients and their level correlates with the increased leukocyte infiltration in synovial tissue." (PMID 21682897, 2011). "Tocilizumab, used for the treatment of rheumatoid arthritis, is a humanized monoclonal antibody against interleukin-6, a cytokine that plays a multifunctional and important role in the immune response." (PMID 21970314, 2011).
rheumatoid arthritis (continued). "IL-6 is a key proinflammatory cytokine that is abundant in the synovium and synovial tissue of patients with rheumatoid arthritis." (PMID 21483764, 2011). "The activity of IL-6 is exerted through IL-6R, and IL-6 is known to play a role in the pathogenesis of a variety of diseases such as Rheumatoid arthritis, Castleman's disease and others." (PMID 21214917, 2011). "Several cytokines, such as IL-1, IL-6 and IL-8, have been found in SF of patients with rheumatoid arthritis (RA)." (PMID 21435227, 2011). "Single nucleotide polymorphisms (SNPs) of transforming growth factor β (TGF-β) and IL-6 genes (respectively, 869C/T and -174G/C) have been associated with radiographic severity of bone-erosive damage in patients with rheumatoid arthritis (RA)." (PMID 21740541, 2011). "The methylation status of IL-6 promoter site was found to be lower in rheumatoid arthritis patients compared to healthy controls." (PMID 21819621, 2011). "IL-8 and IL-6 are among the key regulatory molecules of cartilage destruction in rheumatoid arthritis and are present in synovial fluid of patients with osteoarthritis." (PMID 21682897, 2011). "IL-6 production has also been found to be mediated though the NF-κB pathway in patients with rheumatoid arthritis, retinal microglia, lung pericytes and mice splenocytes treated with LPS." (PMID 21712995, 2011). "A good example of this is Rheumatoid Arthritis where IL-6 has long been used as a biomarker of disease severity." (PMID 20205953, 2010). "Future basic and clinical studies using IL-6 receptor blockers such as Tocilizumab (an anti-IL6R used to treat rheumatoid arthritis) are needed to establish a role for IL-6 in the progression of this secondary pathology." (PMID 20222971, 2010). "For instance, in synovial fibroblasts derived from patients with rheumatoid arthritis, IL-6 signaling can cross-talk with that of IL-1." (PMID 21209948, 2010). "Collectively, these data suggest that IL-6 plays a major role in the pathophysiology of rheumatoid arthritis, and thus support the potential benefit of anti-IL-6 mAb treatment in rheumatoid arthritis patients." (PMID 19368720, 2009). "B cells, which are required for the pathogenesis of G6PI-induced arthritis and also for rheumatoid arthritis, are potent producers of IL-6." (PMID 19640302, 2009). "Rheumatoid arthritis patients have increased IL-6 levels in the morning which correlate with clinical symptoms." (PMID 19785746, 2009). "IL-6-mediated chronic inflammatory proliferation results in the typical plasmacytosis and hyperplasia of synovial cells in the joints of rheumatoid arthritis patients as well as in control animals in our study." (PMID 19368720, 2009). "Dysregulation of IL-6 and TGF-β1 has been linked to an array of inflammatory and pathologic conditions including atherosclerosis, Alzheimer disease, and rheumatoid arthritis." (PMID 19209241, 2009). "Excessive secretion of IL-6 is thought to contribute to the pathogenesis of many diseases such as rheumatoid arthritis." (PMID 18382669, 2008). "Use of this drug (tocilixumab) in phase II clinical trials for rheumatoid arthritis has proved the clinical benefit of IL-6 blockade and we suggest that such a strategy should be applied to hormone-refractory." (PMID 17595657, 2007). "Notably, the E127Q and E127S variants significantly reduced mRNA levels of the key pro-inflammatory cytokines IL-1β and IL-6-central players in the pathogenesis of diseases such as rheumatoid arthritis, gout, and other IL-1-driven conditions." (PMID 41424853, 2026). "Surprisingly, the clinical use of anti-IL6 and anti-IL6Rα agent have been limited to rheumatoid arthritis, Castleman’s disease, and systemic juvenile idiopathic arthritis – all of which have been shown to rely largely on the pro-inflammatory effects of IL6 signaling in driving pathogenicity." (PMID 40961077, 2025).
rheumatoid arthritis (continued). "IL-6 inhibitors, including siltuximab, olokizumab, clazakizumab, PF-04236921, sirukumab, and elsilimomab, represent another class of therapeutics with demonstrated efficacy in conditions like Castleman disease and rheumatoid arthritis." (PMID 40166075, 2025). "These profound and significant results could be valuable for conditions characterized by excessive IL-6 production, such as rheumatoid arthritis and other chronic inflammatory diseases." (PMID 40571694, 2025). "In addition, an intervention study with rheumatoid arthritis demonstrated that vitamin B6 supplementation was able to suppress IL-6 and TNF-alpha production." (PMID 40255391, 2025). "In rheumatoid arthritis patients, IL-1β induces prostaglandin E and collagenase production by synovial cells, promotes bone resorption, and upregulates the production of other pro-inflammatory cytokines, such as GM-CSF and IL-6." (PMID 40136507, 2025). "Recent evidence suggests that Ouabain can inhibit the secretion of pro-inflammatory cytokines, such as tumor necrosis factor-alpha (TNF-α) and interleukin-6 (IL-6), in macrophages, thereby mitigating inflammatory responses in conditions like rheumatoid arthritis and multiple sclerosis." (PMID 40851957, 2025). "Thus, elevated level of IL-6 is pathognomonic sign of inflammation and drugs like Tocilizumab (Actemra) that target IL-6 and/or IL-6R are effective and approved for the treatment of autoimmune diseases including rheumatoid arthritis." (PMID 40114923, 2025). "Therefore, it is of interest to investigate the expression of inflammatory cytokines (TNF-α, IL-1, IL-6, and IL-17) in patients with rheumatoid arthritis (RA)." (PMID 41907960, 2025). "Indeed, the first antibodies against IL-6 and the IL-6 receptor have been developed more than 20 years ago and are in clinical use for patients with rheumatoid arthritis." (PMID 40663802, 2025). "Biologic therapies targeting TNF-α and IL-6 in rheumatoid arthritis may provide dual benefits, improving both joint-related disease activity and neuropsychiatric symptoms such as depression, fatigue, and cognitive dysfunction." (PMID 40943274, 2025). "Similar to IL6R perturbation, IL-6 signaling downregulation through genetic perturbation in IL6 was associated with a lower risk of both polymyalgia rheumatica (odds ratio (OR) per 24% decrease in CRP of 0.76, 95% CI 0.65 to 0.89) and rheumatoid arthritis (OR of 0.87, 95% CI 0.79 to 0.95)." (PMID 40858837, 2025). "However, glucocorticoid resistance often develops, leading to the increased production of pro-inflammatory cytokines such as IL-6, which contribute to chronic inflammation and conditions like rheumatoid arthritis and type 2 diabetes." (PMID 39857306, 2025). "In parallel, Gal-9 is involved in inflammatory activity; indeed, its level was increased in the plasma of patients with rheumatoid arthritis, and its neutralization in fibroblast-like synoviocytic cells of these patients led to a decrease in the production of IL-6." (PMID 41462636, 2025). "Thus, adipose tissue can secrete and release cytokines such as TNFα and IL-6, which are common in inflammatory diseases like rheumatoid arthritis (RA), as well as cytokines known as adipokines (leptin, adiponectin, resistin, and visfatin, among others)." (PMID 40077690, 2025). "This study aims to assess the efficacy and safety of newly approved Janus kinase (JAK) and interleukin-6 (IL-6) inhibitors in patients with moderately-to-severely active rheumatoid arthritis (RA) with inadequate response to or intolerance of conventional disease-modifying antirheumatic drugs." (PMID 39867028, 2024). "It is investigated that the anti-inflammatory properties of mianserin, a serotonin (5HT) receptor antagonist, was able to inhibit the endosomal TLR8 in primary human cells and inhibited the spontaneous release of TNF and IL-6 from rheumatoid arthritis synovial membrane cultures." (PMID 39234104, 2024).
rheumatoid arthritis (continued). "IL-6 is a multifunctional cytokine that participates in the acute response of autoimmune and inflammatory diseases, including autoimmune hemolytic anemia, systemic sclerosis, inflammatory bowel disease, and rheumatoid arthritis, among others." (PMID 38576041, 2024). "However, evidence from clinical and animal studies indicates that IL-6 plays a substantial role in the development of numerous autoimmune conditions, such as rheumatoid arthritis." (PMID 39407182, 2024). "Anti-inflammatory biological agents, including but not limited to TNF-α inhibitors (e.g., Adalimumab and Etanercept), IL-1 inhibitors (e.g., canakinumab), and IL-6 inhibitors (e.g., Tocilizumab), have been used for the treatment of rheumatoid arthritis (RA) and other inflammatory diseases." (PMID 38722915, 2024). "Taken together, these data lend support to the notion that clinically prescribed IL1 and TNF inhibitors for inflammatory conditions (e.g. rheumatoid arthritis) could be used during pregnancy to reduce IL6 trans-signaling and IUI induced adverse consequences." (PMID 38895127, 2024). "Tocilizumab is approved for rheumatoid arthritis and modulates IL‐6 signaling." (PMID 38321574, 2024). "However, exercise has been shown to enhance muscle mass and decrease levels of inflammatory markers, such as TNF-α, C-reactive protein (CRP), and IL-6, in patients with rheumatoid arthritis (RA)." (PMID 38822418, 2024). "Moreover, another study reported that elevated ACRP-30 levels promote IL-8 and IL-6 secretion in rheumatoid arthritis patients, suggesting that augmented adiponectin levels promote the illness." (PMID 38674217, 2024). "Therefore, our study provided preclinical evidence that the fractionated extract of P. sarmentosum Roxb leaf attenuates rheumatoid arthritis complications via the inhibition of IL-6 influx." (PMID 38576490, 2024). "Furthermore, in the synoviocytes of mice with rheumatoid arthritis (RA), miR-365-3p was shown to accelerate apoptosis and inhibit cell proliferation by downregulating the expression of IL-1β and IL-6." (PMID 38338832, 2024). "IL-6 is typically recognized as a pro-inflammatory cytokine that promotes the differentiation of Th17 cells, contributing significantly to autoimmune conditions like rheumatoid arthritis through its role in inducing IL-17A secretion." (PMID 39768138, 2024). "In addition to being a pro-inflammatory marker, IL-6 was also an active factor that has been successfully targeted in some inflammatory disorders, such as rheumatoid arthritis, and that contributed to the pathophysiology of these conditions." (PMID 39575390, 2024). "For example, MR could be theoretically applied to examine whether rheumatoid arthritis (RA) affects circulating levels of IL-6 signalling cytokines." (PMID 38951047, 2024). "For example, it was shown to effectively inhibit Receptor activator of nuclear factor-κB ligand (RANKL) expression by inhibiting the JAK2/STAT3 pathway and upregulating SOCS3 in rheumatoid arthritis fibroblast-like synoviocytes (FLS) stimulated with IL-6/sIL-6R." (PMID 39769302, 2024). "Likewise, it is known that TNF-α is one of the cytokines that perpetuates the inflammatory response, for example, in rheumatoid arthritis, by activating the synthesis of other cytokines such as IL-6." (PMID 39861663, 2024). "IL-6’s wide variety of activity in a range of autoimmune, inflammatory, and infectious diseases has led to various therapeutic interventions being successfully used in the clinic to treat conditions such as rheumatoid arthritis." (PMID 39598462, 2024). "Synovial inflammation plays a central role in the development of rheumatoid arthritis, and its inflammatory milieu is regulated by a complex network of cytokines and chemokines, including tumor necrosis factor, interleukin 6, and possibly granulocyte colony-stimulating factor." (PMID 38217541, 2024).
rheumatoid arthritis (continued). "The probability of developing rheumatoid arthritis illness was not correlated with the IL-4 (590 C/T) or IL-6 (174 G/C) gene polymorphisms in this study." (PMID 38344692, 2024). "In the management of rheumatoid arthritis, reducing IL-6 in joints has shown benefits." (PMID 37627815, 2023). "Furthermore, an IL-6 inhibitor has been recently developed and used as a treatment for rheumatoid arthritis (RA) and Castleman’s disease, with results indicating that the adaptation and use of an IL-6 inhibitor were quite effective." (PMID 36902507, 2023). "Additionally, patients suffering from autoimmune diseases characterized by increased IL-6 levels, such as rheumatoid arthritis, tend to have a higher risk of developing CVD, supporting the role of IL-6 as a risk factor for atherosclerosis." (PMID 37629496, 2023). "Therefore, systemic lupus, rheumatoid arthritis, epileptogenesis, and MS patients have been found to exhibit enhanced inflammation, likely due to dysregulated IL-6 activity." (PMID 37535585, 2023). "Moreover, attenuated TNF-α production has been shown after IL-6 treatment in plasmacytoid dendritic cells in rheumatoid arthritis." (PMID 37908302, 2023). "Moreover, the direct administration of crocin is reported to inhibit the production of IL-6 in vitro and in vivo in an experimental model of rheumatoid arthritis in mice." (PMID 37627614, 2023). "TNF-α, IL-1β, and IL-6 are potent pro-inflammatory cytokines exerting pleiotropic effects on various cell types and play a critical role in the pathogenesis of chronic inflammatory diseases, such as OA and rheumatoid arthritis (RA)." (PMID 36846635, 2023). "Similarly, IL-32β overexpressing mice showed reduced levels of proinflammatory cytokines TNF-α, IL-6, and IL-1β in a murine model of rheumatoid arthritis, which improved arthritic inflammation in these mice." (PMID 37727785, 2023). "In studies on patients with rheumatoid arthritis (RA), a hypothesis was proposed regarding a possible increase in the production of IL-8 and IL-6 induced by leptin." (PMID 38203376, 2023). "Dysregulation of IL-6 axis is known to be involved in the inflammatory pathways of several autoimmune disorders such as rheumatoid arthritis, Castleman’s syndrome, idiopathic juvenile arthritis, neuromyelitis optica spectrum disorder, autoimmune epilepsy and others." (PMID 37841263, 2023). "In summary, urinary IL-6 levels appear to be a surrogate marker for serum IL-6 concentrations, and sequential monitoring of urinary IL-6 levels may be used to evaluate drug response aiming to lower autoimmune reactions in rheumatoid arthritis." (PMID 37189804, 2023). "Nonvascular diseases associated with IL-6 include rheumatoid arthritis, systemic lupus, and osteoporosis." (PMID 36828892, 2023). "Urinary IL-6 levels are also upregulated in rheumatoid arthritis and may become an early marker for kidney transplant rejection, while fecal IL-6 levels are increased in decompensated liver cirrhosis and acute gastroenteritis." (PMID 37189804, 2023). "In rheumatoid arthritis, miR‐221 was higher in patients with high disease activity, and the reduction of inflammatory cytokines (TNFa, IL‐6, and IL‐1β) by inhibition of miR‐221 suggests that it may be a target for treatment." (PMID 37632245, 2023). "Besides the local inflammatory effects, systemic IL-6 impacts the disease burden in patients with rheumatoid arthritis." (PMID 37831074, 2023). "As discussed, IL-6 contributes to the pathogenesis of rheumatoid arthritis (reviewed in Ref." (PMID 36105611, 2022). "The association of IL-6 rs2069837, and rs13306435 polymorphisms with the risk of rheumatoid arthritis and lumbar disc disease were assessed, but not studies on ONFH." (PMID 34986839, 2022). "Besides cytokines that are mainly produced by monocytes/macrophages, such as TNF-α and IL-6, T lymphocytes were reported to participate in the production of some inflammatory cytokines in rheumatoid arthritis." (PMID 35335895, 2022).